BGN (biglycan)
Diseases named in the same sentence as BGN in open-access papers (continued):
Sharing a sentence is not in itself a finding about the gene and the disease.
tumor (continued). "Given the importance of the EMT process for tumor progression, it was of interest if BGN, too, as a common downstream effector impacts these targets in the same way as RAC1b and TAp73." (PMID 38255305, 2024). "In high metastatic tumors, the tumor microenvironment influences EC epigenome promising upregulation of biglycan expression by DNA demethylation and enabling tumor intravasation and metastasis." (PMID 38426109, 2024). "In contrast, biglycan was shown to regulate desmoplasia in colorectal cancer by inhibiting migration and invasion of these tumor cells in 2D and 3D co-culture systems." (PMID 39334952, 2024). "Circ-BGN is overexpressed in resistant tumor cells, and its expression correlates with poorer patient survival." (PMID 39759144, 2024). "Up-regulation in BGN, PEDF, THBS-2, and βIGH3 associated with PDAC progression, as players in tumor microenvironment, cell proliferation, or angiogenic processes." (PMID 39062863, 2024). "The upregulation of several genes, such as lysyl oxidase, suprabasin, and biglycan enhances the migration and tube-forming capacity of tumor endothelial cells." (PMID 38576482, 2024). "In summary, our findings revealed thatPDK1 silencing inhibits the EMT process, migration, and invasion of EOC cells, as well as tumor growth and metastasis, in mice by regulating BGN." (PMID 39578715, 2024). "BGN overexpression partially reverses the anti-tumor effects of PDK1 depletion on EOC cell malignant behaviors." (PMID 39578715, 2024). "Biglycan is upregulated in tumor endothelial cells of metastatic tumors, facilitating the migration of toll-like receptor 2/4+tumor cells, which increases circulating tumor cells and lung metastasis." (PMID 38576482, 2024). "A recent study found that biglycan, an angiocrine factor, from tumor ECs stimulates tumor cells to metastasize." (PMID 39003681, 2024). "Tumor cell intravasation and metastasis can be promoted by biglycan through the NF-kB and ERK signaling pathways." (PMID 36765749, 2023). "TECs express high levels of adhesion molecules and biglycan, which allow vascular endothelial cells to bind to tumour cells, protecting them from circulating anoikis and promoting their metastasis to distant organs." (PMID 37389120, 2023). "IHC staining displayed that BGN expression was obviously higher in PM foci than GC primary foci, and was distributed in cytoplasm of tumor cells and stroma." (PMID 36632455, 2023). "Patients with a high biglycan level in tumor tissue thus showed a worse response to immunotherapy and a smaller number of tumor-infiltrating CD8+ T cells than did those with a low biglycan level." (PMID 37174001, 2023). "In most of the cancers, BGN was significantly up‐regulated in tumor tissues, compared with that in unpaired or paired normal tissues." (PMID 36772945, 2023). "Both in vitro and in vivo experiments demonstrated that BGN promoted tumor progression and transformation of MCs into CAFLCs through the TLR2/TLR4/NF-κB signaling pathway." (PMID 36632455, 2023). "Taken together, mutual interaction between tumor cells and activated MCs mediated by a BGN/FAP-STAT3 positive feedback loop facilitates PM of GC and provides a potential biomarker and therapeutic target for GC metastasis." (PMID 36632455, 2023). "Knockout of BGN in E0771 tumor bearing mice reduced tumor angiogenesis, metastasis to the lung and improved efficacy of chemotherapy." (PMID 35053617, 2022). "In the current study, we compared the expression level of BGN in tumor tissues from TCGA and normal tissues from TCGA and GTEx." (PMID 35154268, 2022). "Tumour endothelia further exploit these pro-angiogenic effects by epigenetically activating BGN expression via hypomethylation of its promoter." (PMID 34982945, 2022). "In this study, through analysis of public datasets and immunohistochemical analysis of tissue arrays, we confirmed that BGN expression was higher in tumor tissue than that in normal tissue." (PMID 36110576, 2022).
tumor (continued). "In the GSE65801 dataset, we came to the same conclusion that BGN mRNA level was higher in tumor tissue than the normal tissue." (PMID 36110576, 2022). "Some signaling molecule triggers such as Biglycan can regulate inflammation through CD14 to influence tumor progression." (PMID 36479102, 2022). "BGN has been shown to have functions as a tumor suppressor and an oncogene depending on cellular origin in various tissue specific cancers." (PMID 35053617, 2022). "BGN was found to be secreted by tumor endothelial cells and was able to induce tumor angiogenesis and metastasis." (PMID 35328635, 2022). "Risk factors, like STC1, COL5A2, COL3A1, and BGN, were significantly correlated with poor OS, while BMPR2 and PGLYRP1 were only found to be protective factors in 2 of 33 tumor types." (PMID 36479101, 2022). "In some types of these cancers, high expression of BGN enhances the ability of invasion and metastasis of tumor cells or contributes to poor prognosis." (PMID 36110576, 2022). "Higher BGN expression was observed in tumor tissues relative to adjacent normal tissues for multiple cancer types." (PMID 35053617, 2022). "Biglycan secreted from TECs can also induce proangiogenic effects in an autocrine manner and has been shown to promote tumor cell intravasation and metastasis through the NF-κB and ERK signaling pathways." (PMID 33966638, 2021). "In cancer-associated fibroblasts (CAF), proteoglycan synthesis shifted from DCN to versican, biglycan, and type I collagen, resulting in tumor-supportive ECM formation, which allowed the spreading of the tumor." (PMID 34884232, 2021). "In this review, we summarize growing evidence for the complex roles of decorin and biglycan signaling in tumor biology and address potential novel therapeutic implications." (PMID 34917515, 2021). "Biglycan expression was undetectable in the normal colonic mucosa, but expressed at highly increased levels in the tumor tissue, especially in the stroma." (PMID 35008869, 2021). "Here we observed that paclitaxel had a significantly greater effect on tumor growth in biglycan knockout mice compared to WT mice." (PMID 33966638, 2021). "This study for the first time revealed that BGN was a potential biomarker for the prediction of GC prognosis and tumor immune infiltration." (PMID 34868341, 2021). "Aberrant expression of BGN in tumors indicate its promoting effects in migration and invasion abilities of tumor cells." (PMID 35096572, 2021). "mRNA vaccines encoding these tumor antigens (THBS2, FSTL3, TNNT1, BGN, CTHRC1, and NOX4) induce a cell-mediated immune response and humoral immune response that are beneficial for efficient clearance of cancer cells." (PMID 35127707, 2021). "Recognizing that data from in silico databases are heterogeneous (containing information from both tumor and stromal cells), which can influence the levels of BGN expression, we have performed an immunohistochemistry analysis in a small cohort of GC tissues." (PMID 33809543, 2021). "Tumor development by L1-expressing CRC cells was much reduced when the levels of endogenous biglycan were suppressed by shRNA." (PMID 35008869, 2021). "Univariate analysis revealed that sex, tumor marker, SCC, histology, stage, T factor, N factor, ly factor, and BGN expression in tumors were significantly associated with recurrence." (PMID 33709550, 2021). "Since changes in ECM proteins and their organization around the tumor tissue are a hallmark of cancer progression, we turned to investigate the small leucine-rich ECM protein biglycan whose levels in the secretome increased manyfold upon L1 transfection." (PMID 35008869, 2021). "This study for the first time revealed that BGN was a potential biomarker for GC tumor immune infiltration." (PMID 34868341, 2021).
tumor (continued). "Biglycan acts as a DAMP, and here we provided evidence demonstrating that stromal biglycan promotes TNF-α expression in tumor cells through binding to TLR2 or TLR4, and subsequent activation of NF-κB and ERK signaling pathways." (PMID 33966638, 2021). "We have previously shown that biglycan is secreted from tumor endothelial cells and induces tumor angiogenesis and metastasis." (PMID 33966638, 2021). "This study provided new insights on biglycan role in GC that should be taken in consideration as a key cellular regulator with major impact in tumor progression and patients’ clinical outcome." (PMID 33809543, 2021). "The cut‐off value for BGN expression in tumor blood vessels for survival analyses was validated by a chi‐square test and the value with the largest significant difference between the two groups was set as the cut‐off value." (PMID 33709550, 2021). "In the current study, we found that stromal biglycan inhibition enhanced chemotherapeutic efficacy through normalization of not only the vascular but also the tumor microenvironment, resulting in increased oxygen perfusion and drug delivery." (PMID 33966638, 2021). "Emerging evidence has uncovered the pivotal functions exerted by the small leucine-rich proteoglycans, decorin and biglycan, in affecting tumor growth and progression." (PMID 34917515, 2021). "The pan-cancer analysis demonstrated that BGN was differentially expressed and related to tumor-infiltrating immune cells across human cancers." (PMID 34868341, 2021). "Upregulation of BGN was markedly correlated with tumor size (p = 0.023), serosa invasion (p = 0.002) and surprisingly, length of hospitalization (p = 0.038)." (PMID 35096572, 2021). "To examine this further, we clarified the potential impact of BGN in the tumor immune response process." (PMID 35096572, 2021). "Bgn mRNA expression was significantly higher in E0771-TECs compared to CD31-negative cells and dermal ECs, indicating that TECs were a source of biglycan in E0771 tumor." (PMID 33966638, 2021). "Second, because we have reported that BGN induced tumor cell intravasation and metastasis in an in vivo mouse model, an elucidation of the association between BGN expression and distant metastasis with clinical samples would be appropriate." (PMID 33709550, 2021). "The potential role of biglycan in cell survival, migration, and tumor angiogenesis is a starting point for a major role in GC metastasis." (PMID 33809543, 2021). "Functionally, biglycan expressed in cancer cells is involved in tumor growth and progression, depending on tumor type." (PMID 33966638, 2021). "Relapse‐free survival was significantly lower in cases with high BGN expression in the tumor (p = 0.007)." (PMID 33709550, 2021). "We also reported that BGN is strongly expressed in vivo in human tumor vessels and in mice, and was detected in the serum of cancer patients." (PMID 33709550, 2021). "We also observed that biglycan depletion in stroma suppressed tumor fibrosis as well as downregulated collagen I expression." (PMID 33966638, 2021). "To investigate how stromal biglycan affects tumor growth in vivo, we orthotopically implanted murine E0771 breast carcinoma cells into the mammary fat pads of WT and Bgn KO female mice." (PMID 33966638, 2021). "Biglycan is a small proteoglycan, whose activity triggers tumor cell migration by nuclear factor-κB and extracellular signal-regulated kinase 1/2 signaling." (PMID 34073394, 2021). "This study for the first time comprehensively revealed that BGN was a potential biomarker for the prediction of GC prognosis and tumor immune infiltration." (PMID 34868341, 2021). "Currently, a number of studies have indicated that the expression level of BGN is significantly higher in tumor tissues than in adjacent normal tissues." (PMID 34356118, 2021). "Intriguingly, several studies indicated that WISP1 was functionally related to BGN in tumor development." (PMID 33117706, 2020).
tumor (continued). "The extracellular PG, biglycan, has a vital role in controlling inflammation and is also reported to be a tumor promoter by regulating growth factor and cytokine signaling pathways." (PMID 32847060, 2020). "Biglycan secreted from tumor vascular endothelial cells promotes invasion and metastasis of cancer cells through activation of NFkB and ERK1/2." (PMID 32821344, 2020). "The observed accelerated metastasis was the direct result of demethylation of the biglycan promoter region, its upregulated expression and activated tumor cell migration via biglycan-dependent activation of NF-κB and extracellular signal-regulated kinase 1/2." (PMID 32283668, 2020). "Biglycan contributes to tumor growth partly due to the fact of its capability to stimulate inflammation-related angiogenesis." (PMID 32825245, 2020). "Recktenwald demonstrated that downregulation of biglycan led to the promotion of cell proliferation and migration in HER2+ cell lines, suggesting that biglycan also has an inhibitory effect on tumor cells." (PMID 33163489, 2020). "Biglycan is a leucine-rich proteoglycan whose overexpression is related to enhanced angiogenesis and tumor invasion." (PMID 32984024, 2020). "On the other hand, biglycan expression is induced in tumor vascular endothelial cells by promoter demethylation." (PMID 32821344, 2020). "The summarized regulation of immunity responses by biglycan can conceivably affect the development and resolution of early pre-cancerous lesions as well as the progression of inflamed tumor subtypes." (PMID 31068944, 2019). "Abnormal BGN expression in tumor tissues suggests that it plays an oncogenic role in cancer migration and invasion." (PMID 31739592, 2019). "High expression levels of BGN have also been detected in a variety of human epithelial cancers, indicating a potentially important role in tumor development." (PMID 31950035, 2019). "In contrast, biglycan acts as a danger signal by affecting both immune responses and tumor characteristics." (PMID 31608236, 2019). "Treatment with collagen and biglycan mimicked the tumor spheroid compaction induced by osteocyte spheroids or osteocyte-derived conditioned medium." (PMID 29615735, 2018). "Mass spectrometry analysis followed by 3D spheroid-based validation revealed that collagen and biglycan are two candidate proteins responsible for compacting tumor spheroids." (PMID 29615735, 2018). "Biglycan is reported to induce inflammatory reactions and stimulate tumor cell migration via nuclear factor κB and extracellular signal-regulated kinase 1/227." (PMID 29615735, 2018). "Mass spectrometry analysis identified several bone matrix proteins in MLO-A5-conditioned media as potential secretory factors responsible for tumor compaction, including collagen, biglycan, and osteonectin." (PMID 29615735, 2018). "The biglycan that was secreted from TECs increased the number of circulating tumor cells and lung metastases in vivo." (PMID 29695087, 2018). "In a multivariate analysis, biglycan expression positively correlated with tumor thickness, Clark level and tumor stage." (PMID 28476030, 2017). "Biglycan knockdown in HM‐TEC decreased the number of circulating tumor cells and lung metastases in vivo." (PMID 28763139, 2017). "Our results also showed that treatment of tumor-bearing mice with a ROS inhibitor reduced the number of tumor blood vessels with downregulation of BGN expression." (PMID 28525375, 2017). "Recently, we observed that in highly metastatic tumors, tumor endothelial cells interact with tumor cells by secretion of a small leucine‐rich repeat proteoglycan known as biglycan." (PMID 28763139, 2017). "ROS inhibition induces antiangiogenic effects with downregulation of BGN in tumor blood vessels in vivo." (PMID 28525375, 2017). "Instead, there were locally abundant cancer cells that synthesized biglycan, a PG highly similar to decorin but with tumour-promoting function." (PMID 28653173, 2017).
tumor (continued). "Since BGN contributes to angiogenesis in TECs and BGN was upregulated by ROS accumulation we treated tumor-bearing mice with DPI, a ROS inhibitor, to examine potential anti-angiogenic effects." (PMID 28525375, 2017). "It was also observed that the epigenetic modification that occurred in the tumor microenvironment was also involved in the increased expression of biglycan in TEC." (PMID 28763139, 2017). "In the present study, we demonstrated for the first time differences in the DNA methylation patterns of biglycan between low- and high-metastatic tumour-derived ECs." (PMID 27295191, 2016). "The biglycan levels in the plasma of HM-tumour-bearing mice were higher than those in the LM-tumour-bearing mice or non-tumour mice." (PMID 27295191, 2016). "When biglycan was knocked down in HM-TECs, tumour cell migration towards HM-TECs was significantly decreased, thereby establishing the requirement for TEC-derived biglycan for tumour cell migration." (PMID 27295191, 2016). "Biglycan, a small leucine-rich repeat proteoglycan secreted from TECs, activated tumour cell migration via nuclear factor-κB and extracellular signal–regulated kinase 1/2." (PMID 27295191, 2016). "The enhanced activation of ERK1/2 in biglycan-stimulated tumour cells was abolished by preincubation with U0126 or TLR2 and/or TLR4 inhibitors." (PMID 27295191, 2016). "LM-tumour cells were then subcutaneously implanted with either control- or biglycan knockdown-HM-TECs." (PMID 27295191, 2016). "Taken together, these data suggest that the NF-κB and ERK pathways are involved in enhanced tumour cell migration by biglycan." (PMID 27295191, 2016). "HM-tumour CM treatment upregulated the expression of biglycan in LM-TECs and made LM-TECs attract more tumour cells, indicating a bidirectional interaction between tumour cells and TECs." (PMID 27295191, 2016). "Expression of biglycan was regulated by DNA demethylation, indicating a bidirectional interaction between tumour cells and TECs in the tumour microenvironment." (PMID 27295191, 2016). "Given that the increased biglycan levels in plasma from mice with LM-tumour cells/HM-TECs was significantly reduced by biglycan knockdown in HM-TECs, HM-TECs are crucially involved in the induction of biglycan." (PMID 27295191, 2016). "Biglycan expression was upregulated in HM-TECs relative to that in other ECs or other cell types, including HM- or LM-tumour cells." (PMID 27295191, 2016). "Biglycan protein enhanced tumour cell migration and this was inhibited by neutralizing the biglycan receptors using an anti-TLR2 or anti-TLR4 antibody." (PMID 27295191, 2016). "Our results provide clear evidence that TECs actively promote tumour metastasis, particularly during intravasation, through the secretion of the small leucine-rich proteoglycan, biglycan." (PMID 27295191, 2016). "As with our findings, BGN knockdown inhibits tumor endothelial cell migration and tube formation in other studies." (PMID 24681892, 2014). "Abnormal BGN expression in tumor tissues suggests that BGN is significant in cancer pathogenesis and progression." (PMID 24681892, 2014). "In line with the fact that BGN exhibits both, inhibitory and promoting effects on tumor cells, controversial roles have been described for BGN in various cancers." (PMID 24223213, 2013). "The present results are in line with the literature suggesting the involvement of BGN in tumor biology and progression." (PMID 24223213, 2013). "In accordance, Kaplan-Meier analysis revealed higher 10-year survival in patients with high biglycan mRNA expression in tumor biopsies." (PMID 24223213, 2013). "In summary, BGN likely modulates tumor biology by effecting important control mechanisms, such as immune responses, matrix assembly and modulation of growth factor activity." (PMID 24223213, 2013). "In this study, we investigated biglycan expression and function in tumour blood vessels and addressed the possibility that it can be a novel TEC marker." (PMID 22374465, 2012).